ABCB1 (ATP binding cassette subfamily B member 1)
Diseases named in the same sentence as ABCB1 in open-access papers (continued):
Sharing a sentence is not in itself a finding about the gene and the disease.
ischemic stroke (11 papers, 2012 to 2025). A stroke disorder caused by obstruction of blood flow to the brain, due to thrombotic (local blood clot formation) or embolic (due to a blood clot or other material traveling from another site) event. "This study aims to evaluate the effect of ABCB1 polymorphism on clopidogrel response variability in ischemic stroke patients and its genotype frequency." (PMID 38914966, 2024). "In Indonesia, this study is the first to investigate ABCB1 gene polymorphisms in relation to clopidogrel response variability in ischemic stroke patients." (PMID 38914966, 2024). "This study aims to investigate the relationship between ABCB1 gene polymorphisms and variability in clopidogrel response among ischemic stroke patients, particularly related to its role in clopidogrel absorption." (PMID 38914966, 2024). "Though no heterogeneity could be detected, the meta-analysis illustrated that ABCB1 C3435T polymorphism was unrelated to the rate of ischemic stroke in patients treated with clopidogrel (for CT + TT vs. CC: OR, 1.03; 95% CI, 0.54 to 1.96; P = 0.93)." (PMID 23056288, 2012). "Comprehensive bioinformatics analysis identified three hub genes—OAS2, TMEM106A, and ABCB1—with high prognostic value for ischemic stroke." (PMID 40371070, 2025). "By integrating machine learning with multi-omics bioinformatics, we established a novel three-gene signature (OAS2, TMEM106A, ABCB1) for precise diagnosis of atherosclerosis and ischemic stroke." (PMID 40371070, 2025). "The ABCB1 results were not significant, which was inconsistent with another study that showed that hypomethylation of the ABCB1 promoter is related to a poor response to clopidogrel in ischaemic stroke patients." (PMID 28358842, 2017). "In the present study, the potential correlation between ABCB1 genotype and ischemic stroke recurrence was examined in patients treated with clopidogrel." (PMID 25452814, 2015). "Furthermore, we established a gene panel that includes OAS2, TMEM106A, and ABCB1 to evaluate their potential in predicting the diagnosis of atherosclerotic plaques and ischemic stroke." (PMID 40371070, 2025). "Furthermore, our results indicate that OAS2, TMEM106A, and ABCB1 may serve as promising candidates for the diagnosis and assessment of atherosclerotic plaques and ischemic stroke." (PMID 40371070, 2025). "For example, P-glycoprotein (P-gp/ MDR1/ ABCB1), a particularly important ABC transporter that is responsible for handling a wide variety of endogenous substrates and xenobiotics, is upregulated after ischemic stroke in rodents." (PMID 32060970, 2020).
rheumatoid arthritis (11 papers, 2015 to 2025). A chronic, systemic autoimmune disorder characterized by inflammation in the synovial membranes and articular surfaces. "Carriers of the ABCB1 rs3842 variant allele (C) were found to have lower disease activity scores in a study including patients with rheumatoid arthritis who received methotrexate." (PMID 36145636, 2022). "ABCB1 expression was inhibited by CsA in the peripheral blood monocytes of rheumatoid arthritis patients." (PMID 36432633, 2022). "Summing up, our results demonstrate that patients with active rheumatoid arthritis have an increased function of ABCB1 and ABCG2, and that disease activity is the variable with the strongest association with this phenomena, even though there is also an association with treatment duration." (PMID 27442114, 2016).
Thrombocytopenia (11 papers, 2016 to 2025). A reduction in the number of circulating thrombocytes. "In multivariate analysis ABCB1 c.1236C>T and ABCB1 c.3435C>T recessive model (CC + CT vs. TT) had increased risk of thrombocytopenia and grades 2 and 3 neurotoxicity, respectively." (PMID 33326171, 2021). "The ABCB1 c.1236C>T was associated with increased risk of thrombocytopenia (OR: 0.15, 95% CI: 0.03–0.82, P = 0.03), whereas ABCB1 c.3435C>T had increased risk of grade 2 and 3 neurotoxicity (OR: 3.61, 95% CI: 1.08–121.01, P = 0.03) in recessive model (CC + CT vs. TT)." (PMID 33326171, 2021). "In addition, the ABCB1 c.1236C>T and ABCB1 c.3435C>T (recessive model: CC + CT vs. TT) genotype had increased risk of thrombocytopenia and grade 2 and 3 neurotoxicity, respectively." (PMID 33326171, 2021). "In addition, ABCB1 c.1236C>T and c.3435C>T is associated with a higher risk of thrombocytopenia and neurotoxicity." (PMID 33326171, 2021). "Genotyping for ABCG2 rs2231142, ABCB1 rs1128503 and rs2032582 polymorphism could become a clinical routine practice to select the appropriate dose to decrease the risk of sunitinib-induced thrombocytopenia and HFS in Asians while ensuring efficacy." (PMID 33762959, 2021). "The ABCB1 c.1236C>T (recessive model: CC + CT vs TT) was more common in women with thrombocytopenia (28%) compared with those with no toxicity (9%, P = 0.03)." (PMID 33326171, 2021).
COVID-19 (10 papers, 2020 to 2024). A disease caused by infection with severe acute respiratory syndrome coronavirus 2. "Over 30% of the Thai patients inherited C3435T ABCB1 genetic polymorphisms, suggesting that considerable proportion of Thai population be affected by the C3435T ABCB1 genetic variant if taking LPV/RTV for combating COVID-19." (PMID 35250581, 2022). "Amid this emergency situation, it is suggested to genotype the ABCB1 C3435T genetic polymorphism in order to make LPV/RTV therapy more precise to overcome adverse clinical events or deaths associated with COVID-19." (PMID 33759544, 2021). "Instead, there is a need to focus on the efficacy or safety assessment of LPV/RTV associated with ABCB1 C3435T genetic polymorphism for COVID-19 patients infected with SARS-CoV-2." (PMID 33759544, 2021). "This can be implemented by testing the ABCB1 C3435T polymorphism with the following groups of patients with COVID-19." (PMID 33759544, 2021). "The presence of polymorphic allele of NR3C1 rs6198, ABCB1 rs2032582 or GSTP1 rs1695 polymorphism could predict poorer course of COVID-19 and also poorer treatment outcome." (PMID 39135792, 2024). "It is hypothesized that a considerable proportion of COVID-19 patients treated with lopinavir/ritonavir inheriting ABCB1 C3435T genetic polymorphism may be predisposed to either therapeutic failure or toxicity." (PMID 33759544, 2021). "However, it is reasonably assumed that such genetic effects of ABCB1 may also exist for SARS-CoV-2 infection causing COVID-19." (PMID 33759544, 2021). "As for the European populations, ABCB1 rs1045642 G and ABCB1 rs2032582 C variants are rather frequent (around 50 %) in all of them, and could be relevant for reduced clearance of azithro mycin, lopinavir and ritonavir drugs in COVID-19 patients." (PMID 33312066, 2020). "Compared to BAL samples from healthy individuals, BAL samples from COVID-19 patients with mild or severe symptoms showed an increased number of cells with detectable levels of MDR1 (ABCB1) transcripts." (PMID 33622961, 2021). "By mining scRNA-seq data from BAL samples of COVID-19 patients and healthy controls (n = 12) for ABCB1 expression, we considered the genetic variability on the ABCB1 locus beyond that present in our two model systems." (PMID 33622961, 2021). "There are approximately 50 SNPs of the ABCB1 gene; therefore, it is extremely difficult to predict which SNP would be linked to PK effects of LPV/RTV affecting efficacy or safety in COVID-19 patients." (PMID 33759544, 2021). "Variants in CYP3A4, CYP3A5, CYP2C8, CY2D6, ABCB1, ABCC2, and SLCO1B1, among other variants, could be included in pharmacogenetic studies of COVID-19 treatment." (PMID 33807592, 2021). "To address these issues, we investigated transcript levels of ABCB1 in bronchoalveolar lavage (BAL) samples from healthy individuals and from COVID-19 patients with mild or severe symptoms from a previously published data set." (PMID 33622961, 2021). "We have shown that rather frequent PGx markers, ABCB1 rs1045642 and ABCB1 rs2032582 (AAF around 50%), could be relevant for reduced clearance of azithromycin, lopinavir and ritonavir drugs and UGT1A7 rs17868323 (AAF 66.2%) for hyperbilirubinemia in ritonavir treated COVID-19 patients in Serbia." (PMID 33312066, 2020). "This might indicate that COVID-19 patients from Europe, Asia and America may be more vulnerable to either therapeutic failure or toxicity of LPV/RTV if ABCB1 C3435T genetic variability is not considered." (PMID 33759544, 2021).
mucositis (10 papers, 2017 to 2025). Mucositis is inflammation and damage of the mucous membranes lining the mouth and other parts of the gastrointestinal (GI) tract. "In accordance with the ABCB1 expression, its rs2032582 polymorphism was associated with irinotecan-induced severe mucositis in metastatic colorectal cancer patients." (PMID 33799730, 2021). "This study shows the ABCB1 rs1128503 variant is a promising predictor of irinotecan-induced severe gastrointestinal toxicity, in particular diarrhea and mucositis." (PMID 32695000, 2020). "ABCB1 rs1045642 was associated with risk of mucositis (P = 0.031), while PIK3R1 rs10515074 and RAPTOR rs9906827 were associated with hyperglycemia and non-infectious pneumonitis (P = 0.016 and 0.024, respectively)." (PMID 28727815, 2017). "For mucositis, patients with the T-allele of ABCB1 rs1045642 had higher risk of toxicity (OR = 2.30, 95%CI = 1.08–4.77, P = 0.031; multivariable analysis)." (PMID 28727815, 2017). "For instance, the associations between MTHFR 677C>T (rs1801133) and an increased risk of hepatotoxicity and mucositis are demonstrated by meta-analysis of nine studies, while the associations between ABCB1 3435C>T (rs1045642) and hepatotoxicity are supported by meta-analysis of only three studies." (PMID 34744734, 2021). "In line with this study, and after adjusting for clinicopathological covariates and the UGT1A1*28 genotype in a larger sample, we found that patients with the CC genotype for the ABCB1 rs1128503 variant were at highest risk of diarrhea (P=0.014) and mucositis (P=0.002)." (PMID 32695000, 2020). "In addition, SNPs in ABCB1 were associated with increased risk of mucositis (rs1045642) and lymphopenia (rs2032582)." (PMID 28727815, 2017). "For instance, ABCB1 rs1045642 and ABCC11 rs7194667 have been associated with an increased risk of fluoropyrimidine-induced adverse events, including diarrhea, mucositis, and leukopenia." (PMID 40428413, 2025). "Two variants in ABCB1 (rs1128503 and rs1045642) and one variant in MTHFR (rs1801133) showed association with MTX-induced mucositis in this Chinese cohort." (PMID 36536332, 2022). "No polymorphism was found to be associated with oral mucositis, although it occurred more frequently in patients with the ABCB1 rs1128503C allele (CC and TC) than in those with the TT genotype (OR 2.009, 95% CI 0.987–4.090, P = 0.054)." (PMID 28525903, 2017).
osteonecrosis (10 papers, 2016 to 2025). A none disease characterized by death of bone tissue due to a lack of blood supply. "Aberrant CpG hypermethylation at gene ATP-binding cassette subfamily B member 1 (ABCB1, the encoding gene of P-glycoprotein) leads to osteonecrosis of the femoral head (ONFH)." (PMID 32963550, 2020). "A meta-analysis of genetic risk factors for glucocorticoid-induced osteonecrosis concluded that PAI-1 4G/5G and ABCB1- ATP Binding Cassette Subfamily B Member 1 polymorphisms are risk factors for osteonecrosis." (PMID 30533396, 2018). "Interestingly, several genetic association studies and meta-analyses have reported an association between ABCB1 polymorphisms and steroid-induced osteonecrosis." (PMID 29556197, 2018). "Genetic mutation of alcohol-metabolizing enzyme genes has been associated with alcohol-induced osteonecrosis and polymorphism of NOS3, ABCB1 and IL23R gene are related with developing osteonecrosis." (PMID 28422712, 2017).
serous ovarian cancer (10 papers, 2016 to 2025). "The SLC25A40-ABCB1 fusion is the most common rearrangement involving ABCB1, occurring in 15.7% (20/108) of cases of high-grade serous ovarian cancer." (PMID 34381020, 2021). "We found that in the serous subgroup, the correlation between ABCB1 expression and OS became significant after excluding study specifically identifying high-grade serous ovarian cancer (HGSOC) (HR, 1.31; 95% CI: 1.07–1.59)." (PMID 27812204, 2016). "In addition, upregulation of ABCB1 is associated with the transcriptional fusion of ABCB1 and SLC25A40, which was identified through whole-genome analysis in patients with high-grade serous ovarian cancer (HGSOC) who underwent prior chemotherapy and targeted therapy." (PMID 38539161, 2024). "Also, a recent study showed that in nearly 8% of high-grade serous ovarian cancers with acquired resistance to paclitaxel, translocations and inversions of the 5′ regulatory region of the ABCB1 gene lead to MDR1 overexpression compared to patient-matched, paclitaxel-sensitive primary tumors." (PMID 28032595, 2017). "We found that in the serous subgroup, the correlation between ABCB1 expression and TR became significant in studies specifically identified low-grade serous ovarian cancer (LGSOC) and remained non-significant in studies identified HGSOC." (PMID 27812204, 2016).
colitis (9 papers, 2013 to 2025). Inflammation of the colon. "Analysis of the Abcb1 protein expression level of mouse gene variants confirmed no Abcb1a or Abcb1b in the colon, while gross and microscopic examinations also confirmed the colitis phenotype, in all KO mice." (PMID 37588005, 2023). "Moreover, apart from CVDs, increased expression of ABCB‐1 gene can also reduce the risk of colitis and inflammatory bowel disease 57, suggesting a potential role of IRW in treating several other disease conditions in addition to CVDs." (PMID 26016560, 2015). "It is known that ABCB1 knockout mice (MDR1a−/−) spontaneously develop colitis with pathological phenotypes similar to human UC." (PMID 40191037, 2025). "Colitis was preceded by altered gut bacterial composition, suggesting that the deletion of ATP-binding cassette B1 (Abcb1) led to fundamental changes in host-microbiota interactions in a mouse model." (PMID 34778085, 2021). "Abcb1/mdr1a knock-out mice develop colitis and later intestinal adenocarcinomas suggesting that the absence of ABCB1 confers risk of inflammation-related CRC." (PMID 23977225, 2013). "Using ABCB1 KO mice, different researchers were able to correlate the disrupted function of the transporter with increased inflammation, followed by the development of colitis and GIT dysplasia." (PMID 32587767, 2020). "Therefore, berberine regulate the Abcb1 gene expression through Nrf2-mediated pathway when colitis occurs, however, may through PXR-mediated pathway in a healthy organism." (PMID 31013627, 2019).
lung adenocarcinoma (9 papers, 2017 to 2023). A carcinoma that arises from the lung and is characterized by the presence of malignant glandular epithelial cells. "Among them, ABCB1 is highly expressed in patients with lung adenocarcinoma and associated with poor survival." (PMID 34066059, 2021). "Another study observed that ABCB1 is highly expressed in patients with stage I lung adenocarcinoma and that the expression of this protein is associated with poor survival, which indicates that ABCB1 expression is useful for predicting the prognosis of patients with lung adenocarcinoma." (PMID 32503508, 2020). "In lung adenocarcinoma from 20 patients, higher ABCB1 mRNA and protein levels have been found than in normal adjacent lung tissues." (PMID 33066132, 2020). "Moreover, in another cohort of 30 lung adenocarcinoma patients, we found that ABCB1 expression in tumour cells was positively correlated with ZIP1 expression in CAFs." (PMID 36207295, 2022). "ABCB1 inhibitors can overcome resistance to CDDP, doxorubicin (DXR, an anthracycline antibiotic), and paclitaxel (a taxane-derived chemotherapeutic agent), in human lung adenocarcinoma cells." (PMID 34066059, 2021). "The lncRNA KCNQ1OT1 is highly expressed in lung adenocarcinoma cells and the knockdown of lncRNA KCNQ1OT1 significantly decreased the expression of MDR1/ABCB1 in A549 adenocarcinomic human alveolar basal epithelial/human ovary cells derived from metastatic site (PA1) cells." (PMID 32164712, 2020). "Targeting PLK1 with shRNA or non-functional mutants downregulated ABCB1, ABCC9, and ABCG2 in paclitaxel-resistant lung adenocarcinoma (LUADTXR), similar to the downregulation effects from treatment with PLK1 inhibitors." (PMID 34503223, 2021).
medulloblastoma (9 papers, 2017 to 2023). A malignant, invasive embryonal neoplasm arising from the cerebellum. "Previously, we showed ABCB1 expression to be associated with high-risk medulloblastoma." (PMID 36831428, 2023). "We have previously correlated the expression of ABCB1 with high-risk medulloblastoma patients." (PMID 33948561, 2021). "It is feasible, therefore, that in addition to vincristine sensitivity, YB-1-mediated ABCB1 expression and function contribute to the invasive capabilities of medulloblastoma cells." (PMID 36831428, 2023). "In conclusion, we identified a role for TWIST1 during medulloblastoma metastasis and demonstrate the potential of therapeutically inhibiting ABCB1 with the FDA-approved vardenafil to prevent metastasis." (PMID 33948561, 2021). "In this study, we identified a TWIST1–ABCB1 signaling axis during medulloblastoma migration, which can be therapeutically targeted with the clinically approved ABCB1 inhibitor, vardenafil." (PMID 33948561, 2021). "In common with our previously published findings in medulloblastoma we found that enriching for stemness in neurosphere culture resulted in a 3 fold increase in ABCB1 expression." (PMID 31311995, 2019). "Inhibition of ABCB1 by verapamil and vardenafil sensitize to etoposide, implicating the role of ABCB1 in etoposide export in these medulloblastoma model systems." (PMID 29186899, 2017). "Indeed, ABCB1 protein expression is associated with metastatic medulloblastoma and inhibition of ABCB1 impedes the migratory capacity of medulloblastoma cells." (PMID 36831428, 2023). "We then analyzed whether inhibition of ABCB1 could affect cell aggregation in medulloblastoma cell lines cultured in the 3D-BME model." (PMID 33948561, 2021). "Our work provides evidence that ABCB1 inhibition could provide a promising therapeutic strategy to target TWIST1-induced metastasis in medulloblastoma." (PMID 33948561, 2021). "As anticipated, genetic disruption of YB-1 significantly reduced the expression of ABCB1 mRNA by ~40% in HD-MB03 cells and ~50% in D283 cell lines, further supporting the notion that YB-1 transcriptionally regulates ABCB1 in medulloblastoma cells." (PMID 36831428, 2023). "We have previously shown that the ABCB1 gene is expressed in medulloblastoma cell lines, and the overexpressing MED6-TWIST1 cell line showed a 4-fold increase in ABCB1 gene expression relative to parental MED6 cell line." (PMID 33948561, 2021). "Further genetic knockdown experiments are required to elucidate how TWIST1 is regulating ABCB1 and whether dual TWIST1/ABCB1 inhibition has the potential to prevent medulloblastoma metastasis." (PMID 33948561, 2021).